BRAF (B-Raf proto-oncogene, serine/threonine kinase)
Diseases named in the same sentence as BRAF in open-access papers (continued):
Sharing a sentence is not in itself a finding about the gene and the disease.
melanoma (continued). "Vemurafenib, dabrafenib, and encorafenib are three drugs used to treat BRAF V600E-mutated melanoma." (PMID 35954441, 2022). "Although this is beyond the specific scope of this work, the early identification of intrinsic resistance to targeted therapy could also be important because immunotherapy is indicated in patients with BRAF-mutated melanoma." (PMID 36077693, 2022). "Oncogenic mutations in BRAF were observed in about 40–50% of melanoma patients." (PMID 35837286, 2022). "In 2002 the cancer genome project identified BRAF mutations in more than 60% of melanomas." (PMID 35883549, 2022). "Mutated BRAF is involved in different mechanisms of melanoma progression, including the evasion of senescence and apoptosis, support of the replicative potential, sustained angiogenesis, tissue invasion and metastasis as well as the evasion of the immune response." (PMID 33925387, 2021). "There are few studies on BRAF mutation in Iranian patents with melanoma." (PMID 34567185, 2021). "Efficacy and limitations of targeted therapies for LM from EGFR-mutant and ALK-rearranged NSCLC, HER2-positive breast cancer and BRAF-mutated melanomas are reported, including the use of intrathecal administration or modification of traditional cytotoxic compounds." (PMID 34207653, 2021). "The VE-BASKET and ROAR basket trials explored the efficacy of vemurafenib and the combination of dabrafenib/trametinib, respectively, in BRAF V600 mutation-positive cancers other than melanoma, papillary thyroid cancer, colorectal cancer and non small cell lung cancer." (PMID 33669326, 2021). "This study suggests that Nox4 inhibitors could be associated to the current therapy used to treat melanoma patients with BRAF mutations." (PMID 33451139, 2021). "To address this need, we compared the cost-effectiveness of dabrafenib plus trametinib with vemurafenib as the first-line treatments for previously untreated patients with unresectable stage IIIC or IV melanoma with BRAF V600 mutations from a healthcare system perspective in China." (PMID 34201096, 2021). "BRAF is mutated in 8% of human cancers, primarily melanoma, whereas MEK and ERK are rarely mutated." (PMID 33809714, 2021). "Summary of diagnostic testing modalities used to detect BRAF-mutated melanoma." (PMID 34068774, 2021). "This analysis suggests that melanomas defined by BRAF driver mutations may have increased activity of a mutational process acting specifically on CTCF binding sites." (PMID 33941236, 2021). "BRAF inhibition may be combined with these monoclonal antibodies in patients with melanoma who have both PD-1 positivity and BRAF mutations, but trial data for this combination treatment is still pending at this time." (PMID 35008185, 2021). "Previous successes with anti-B-Raf targeted therapy in tumors with V600E BRAF mutation like melanoma, combined with the poor prognosis and paucity of therapeutic options for GB patients is leading to a growing interest in the potential efficacy of this approach." (PMID 34804975, 2021). "BRAF V600E mutations are essential to guide treatment decision-making: indeed, melanomas harboring BRAF V600 mutations are generally responsive to BRAF inhibitors (BRAFi) and/or MEK inhibitors (MEKi), which, therefore, are the main targeted agents for melanoma therapy." (PMID 34683910, 2021). "We recently provided evidence that panicein A hydroquinone not only increased the effect of classical chemotherapeutic treatments such as doxorubicin and cisplatin but also enhanced the effect of the BRAF inhibitor vemurafenib against BRAF mutated melanoma cells in vitro and in vivo." (PMID 33810240, 2021). "Cell-free DNA–based tests may be a fast and convenient option to identify BRAF mutation status in melanoma patients, and help inform treatment decisions." (PMID 34298804, 2021). "Additionally, a lack of solar elastosis has been described in the adjacent skin of melanomas harboring BRAF mutations, which are a common finding in melanoma." (PMID 34123564, 2021).
melanoma (continued). "A novel RAF inhibitor, LXH254—which may have activity in tumors with concurrent BRAF and NRAS mutations, and in melanoma cell lines that are resistant to BRAF and MEK inhibition—was found to be less active in the KRAS mutant cell lines." (PMID 34830283, 2021). "In addition to its role in bortezomib resistance in MM, SSP’s was also found to contribute to the resistance against BRAF inhibitors used to treat cancers expressing V600E BRAF mutation, such as melanoma, pancreatic and non-small cell lung cancer cells." (PMID 33397437, 2021). "BRAF mutations have been found in half of melanomas, mainly as a V600E mutation." (PMID 33474634, 2021). "Oncogenic mutations in BRAF are reportedly found in approximately 50% of melanoma cases." (PMID 34771678, 2021). "Finally, in melanoma, approximately 40-50% of patients with melanoma harbor a mutation in the serine/threonine kinase BRAF." (PMID 35096602, 2021). "BRAF mutations have been identified in 40–50% of melanoma patients." (PMID 34526609, 2021). "In contrast, STAG2 or STAG3 mutation in melanoma conferred resistance to BRAF inhibition owing to reactivation of MEK-MAPK (ERK) signaling, which suggests that in a melanoma context, STAG2 mutation status could inform therapeutics." (PMID 34202641, 2021). "Given the revolution that targeted drugs constituted as inhibitor-based drugs against melanomas harbouring mutations in BRAF, MEK, and KIT, studies like the present one contribute to the identification of potential lines of work aimed at improving the medical attention of these patients." (PMID 34680367, 2021). "Currently, targeted therapy has been successfully used in treating patients with other tumors with BRAF V600E mutation, namely, melanoma, non small cell lung cancer (NSCLC), papillary thyroid cancer, hairy cell leukemia, colon cancer in combination with Cetuximab." (PMID 35155453, 2021). "Targeted therapies, e.g., BRAFi improved patient outcomes in BRAF mutated melanoma." (PMID 34063443, 2021). "Finally, it is also worth mentioning that EZH2 gain-of-function mutations usually co-occur with BRAF V600E mutations in CM, promote aggressive cell morphologies and enhance melanoma tumor growth in vitro." (PMID 34575678, 2021). "However, while effective against some mutant BRAF-driven cancers, such as melanoma, they proved ineffective against RAS-mutated cancers." (PMID 33920182, 2021). "Dual inhibition of this pathway in patients with unresectable V600 BRAF-mutated melanoma, using combination therapy with BRAF and MEK inhibitors, confers high response rates and survival benefit, although efficacy, in metastatic patients, is often limited by development of resistance." (PMID 33435389, 2021). "More recently, the FDA approved ipilimumab, nivolumab, pembrolizumab, and the dabrafenib plus trametinib combination (BRAF‐mutated patients only) for adjuvant therapy of high‐risk melanoma, based on significantly longer recurrence‐free survival associated with these therapeutic interventions." (PMID 34137219, 2021). "In addition, the RAS/BRAF/MEK/ERK mitogen-activated protein kinase pathway is constitutively activated in melanoma via an activating mutation in BRAF or autocrine growth factor stimulation and is a crucial modulator of melanoma initiation and progression." (PMID 34777692, 2021). "The melanoma samples were analyzed for BRAF mutation status using StripAssay." (PMID 33535453, 2021). "More recently, stage III melanoma patients with BRAF mutations may receive adjuvant treatment with either the combination BRAF and MEK inhibitors, dabrafenib and trametinib or immunotherapy." (PMID 34537078, 2021). "As supporting evidence, we may mention the transforming activity of the viral v-RAF oncogene (a truncated version of c-RAF) or the frequent detection of BRAF mutations in malignant melanomas, thyroid cancer or other malignancies at a lower rate." (PMID 34062774, 2021).
melanoma (continued). "Another recent multicenter retrospective analysis investigated the retreatment with BRAFi and MEKi combination in 51 patients with metastatic BRAF-mutated melanoma, previously progressed after receiving kinase inhibitors (BRAFi and MEKi or BRAFi alone) and immunotherapy (anti-PD-1 or anti-CTLA-4)." (PMID 34136385, 2021). "Like Pathway 1 to melanoma, dysplastic nevi are associated with activating mutations of BRAF or NRAS; additional mutation of the TERT promoter and, sometimes, hemizygous loss of CDKN2A are involved in the morphological progression to a “classical” (superficial spreading) melanoma in situ." (PMID 34277420, 2021). "The same mutation in BRAF that is found in moles is also present in half of all cases of melanoma." (PMID 34812139, 2021). "BRAF inhibitors are used to treat late-stage melanoma patients harbouring BRAF mutations." (PMID 33741929, 2021). "Conversely, MC1R variants are inversely correlated with BRAF V600K-positive melanomas." (PMID 34442055, 2021). "Indeed, tumors harboring TERT-p mutation at high frequency, such as melanoma, thyroid papillary carcinoma, and glioma, are also well known for a high frequency of BRAF mutation." (PMID 33635430, 2021). "The most common somatic mutation in melanoma is the V600E substitution in BRAF." (PMID 35186949, 2021). "BRAF mutation displays unfavorable prognostic value compared to wild type melanomas, although may benefit of approved combination therapy with BRAF and MEK inhibitors (dabrafenib plus trametinib or vemurafenib plus cobimetinib)." (PMID 34207514, 2021). "A total of 20 patients (16.1%) had BRAF-mutated melanoma; 14 patients (11.3%) had brain metastasis." (PMID 34115870, 2021). "However, only a few studies with heterogeneous results have been published on the relationship between dermoscopic patterns of melanoma and BRAF mutational status." (PMID 33954019, 2021). "Mutant BRAF can be pharmacologically inhibited, which in combination with blockade of its direct effector, MEK1/2, is an FDA-approved therapeutic strategy for several BRAF-mutated cancer patients, such as melanoma, non-small-cell lung carcinoma, and thyroid cancer." (PMID 34298710, 2021). "In this review, we summarize the current understanding of BRAF mutations in melanoma." (PMID 34066966, 2021). "The most prevalent significantly mutated genes in melanoma such as BRAF, NRAS, KRAS, HRAS, and NF1 were also explored; the results indicated that the high-FRGs score group have lower mutation frequencies in NRAS, KRAS, and NF1 compared to the low-FRGs score group." (PMID 34745259, 2021). "Another small molecule inhibiting Bcl-2, Bcl-xL and Bcl-w is represented by ABT-737, whose effect on melanoma was demonstrated because of its ability to empower the efficacy of several therapeutic strategies including immunotoxins and BRAF or MEK inhibitor in BRAF-mutated cells." (PMID 33803452, 2021). "Interestingly, ZEB1-AS1 expression is significantly higher in BRAF- or RAS-mutated melanomas, when compared to triple-negative (BRAFWT, NRASWT, NF1WT) melanoma cells, whereas ZEB1 expression is higher only in BRAFmut melanomas." (PMID 34638331, 2021). "Furthermore, it has been shown that mutation in BRAF induces the production of IL-1α and –β in melanoma cells, which in turn enhances MAF’s capability to suppress the proliferation and function of cytotoxic T cells." (PMID 34067929, 2021). "Furthermore, patients with BRAF V600E mutated melanomas respond to FDA-approved BRAF inhibitors, such as atezolizumab." (PMID 34589115, 2021). "However, the relationship between BRAF V600E mutation and the transformation of a nevus to malignant melanoma remains obscure in the Iranian population." (PMID 33391380, 2021). "About 50% of all melanomas are associated with BRAF mutations." (PMID 33917428, 2021).
melanoma (continued). "The only targeted therapy combination that does not directly target angiogenesis is the combination of a BRAF inhibitor vemurafenib and a mitogen-activated extracellular kinase (MEK) inhibitor cobinetinib in combination with atezolizumab in advanced melanoma with BRAF V600 activation mutation." (PMID 34579759, 2021). "Patients with BRAF mutation-positive melanoma have high ORRs with BRAF and MEK inhibitors." (PMID 33827575, 2021). "In addition, the previous report shows that BRAF mutation promotes melanoma tumor growth through reduction of OXPHOS41." (PMID 33446631, 2021). "However, mutations in BRAF are prominent and inhibition of BRAF is a common, standard therapy for the treatment of BRAF-mutant melanoma." (PMID 33801965, 2021). "Melanoma with BRAF mutations appears to benefit from targeted BRAF and MEK therapy." (PMID 34805163, 2021). "The frequent mutational activation of BRAF in melanoma led to the development of type I small molecule inhibitors to inhibit the constitutive activity of the most common RAF variant in cancer, BRAFV600E, which is active as a monomer in contrast with wild-type RAF which signals as a dimer." (PMID 33367512, 2021). "Moreover, BRAF-mutated melanomas are more common in younger patients whereas NRAS mutations are encountered in older patients and in the nodular histological subtype." (PMID 34123788, 2021). "Moreover, SIJ1777 is capable of inducing apoptosis and blocking significantly migration, invasion, and anchorage-independent growth of melanoma cells harboring BRAF class I/II/II mutations." (PMID 33917428, 2021). "Furthermore, BRAF-mutated melanoma is connected with shorter survival in stage IV disease and V600E expressed in the nucleus (rather than the cytoplasm) is associated with more advanced tumour staging, lymph node metastasis and depth of invasion." (PMID 34441278, 2021). "Other studies identified treatment resistance mechanisms to targeted treatment against the mutated BRAF serine/threonine protein kinase including repression of the melanoma differentiation gene microphthalmia-associated transcription factor (MITF) and induction of AXL receptor tyrosine kinase." (PMID 33535416, 2021). "It is well known that prooncogenic BRAF V600E-mutation could drive the malignant biological properties of melanoma cells." (PMID 34526571, 2021). "Similarly, mutations involving BRAF, which are prevalent in malignant melanoma, exert an oncogenic effect by activating the downstream MEK/ERK MAPK pathway, resulting in uncontrolled cellular proliferation." (PMID 34685488, 2021). "Our findings not only demonstrate that bilirubin is an unfavorable for patients with BRAF-mutant melanoma who received vemurafenib treatment, but also uncover the underlying mechanism by which bilirubin restrains the anticancer effect of vemurafenib on BRAF-mutant melanoma cells." (PMID 34222023, 2021). "In mucosal melanomas, the BRAF and NRAS mutations are infrequent, which may reflect the lack of sunlight exposure." (PMID 34063141, 2021). "Interestingly, BRAF mutations were less likely to occur on volar or ungual melanomas than on dorsal acral skin, probably reflecting the increased role of UV exposure." (PMID 33525348, 2021). "Activating somatic mutations in BRAF are present in approximately 50% of advanced melanomas." (PMID 34109763, 2021). "Employing senolytics to eliminate BRAF‐senescent melanocytes within nevi in patients at risk of developing melanoma might then be an efficient strategy for preventing malignant transformation." (PMID 34355491, 2021). "MAP kinase, PI3K, and V600E mutation in BRAF oncogene are common features in melanoma and TC." (PMID 33578751, 2021). "Studies have illustrated the benign nature of such naevi as they remain dormant for decades posing little oncological threat, indicating the BRAF mutation alone may be insufficient to potentiate melanoma tumorgenesis." (PMID 34155457, 2021).
melanoma (continued). "Interestingly, with most MAPK pathway mutations, the murine sarcoma viral oncogene homolog mutation, also known as BRAF mutation, is present in 40-60% of melanomas, and the neuroblastoma ras viral oncogene homolog mutation is found in 15-30%." (PMID 34868763, 2021). "Here, we will describe the molecular pathways deregulated in melanoma, conferring resistance to BRAF inhibition which could also be affected by the loss of RASSF1A." (PMID 34066022, 2021). "Tissue specimens from patients with melanoma and/or TC show a high rate of the BRAF V600E mutation." (PMID 33578751, 2021). "In addition, the majority of shared neoantigens observed are BRAF mutations (64 of 78, 82%), a known driver mutation for melanoma and previously documented in as many as 66% of all malignant melanoma cases." (PMID 35611186, 2021). "Intriguingly, BRAF-mutated melanomas may induce distinct alterations of the TME, which may serve as an additional mechanism of immune resistance." (PMID 34576054, 2021). "A key difference in the melanoma mutational profiles between Asians and Caucasians is that in Caucasians, most melanomas, which are predominantly cutaneous melanomas, are driven by UV-induced point mutations, including driver mutations in BRAF and NRAS." (PMID 34149718, 2021). "In vitro studies have shown that BRN2 expression is induced by a range of melanoma-associated signaling pathways including activation of the mitogen-activated protein kinase (MAPK) pathway downstream from BRAF, the PI3K pathway, the LEF-β-catenin axis, as well as FGF, TNF-α, EDN3, and SCF signaling." (PMID 34140478, 2021). "Environmental cues, not oncogene-induced senescence, may stop melanocytes with an activating mutation in the BRAF gene from turning into melanoma." (PMID 34882087, 2021). "The BRAF mutation is harbored by approximately 50% of melanomas." (PMID 34447613, 2021). "Similarly, melanomas in young patients with low cumulative solar ultraviolet light exposure are 2.7 times more likely to show BRAF (B-Raf Proto-Oncogene) mutations." (PMID 34912708, 2021). "Since some chemosynthetic small-molecule drugs could enter the cytoplasm to inhibit BRAF mutation and treated melanoma, some small-molecule drugs that can specifically inhibit or degrade CENP-N could be designed to treat nasopharyngeal cancer in the future." (PMID 34893086, 2021). "Interestingly, while BRAF V600E-mutated melanomas show sensitivity to BRAF-mutant inhibitor vemurafenib, efficacy in mCRC is limited." (PMID 34769209, 2021). "Furthermore, it has been demonstrated that melanomas harboring BRAF mutations share certain morphological features detectable with noninvasive diagnostic tools such as dermoscopy." (PMID 33954019, 2021). "Notably, the three-drug combination identified in our NF1/PTEN-mutant melanoma model also showed anti-melanoma activity in BRAF-mutant melanoma cells harboring PTEN-mutation." (PMID 34331013, 2021). "Interestingly, mutations of BRAF have been demonstrated in more than 80% of benign nevi, including the precursors of melanoma." (PMID 33391380, 2021). "However, in melanomas harboring both BRAF and NF1 mutations, it is more likely that tumors can escape from MAPK inhibiting therapy." (PMID 34350118, 2021). "On the other hand, the 17 upregulated and the 2 downregulated plasma metabolites commonly detected in both BRAF-mutated melanoma xenograft variants versus NTM could be due to the BRAF mutation and associated oncogenic signaling." (PMID 33498757, 2021). "These mutations have also been significantly associated with BRAF mutations in melanoma." (PMID 34290704, 2021). "Recent research has established that BRAF mutations could be linked with shorter DFS in early stages of melanoma." (PMID 34441278, 2021). "Additionally, reverse-hybridization StripAssay was carried out on melanoma samples detecting BRAF mutation." (PMID 33535453, 2021).